GPX1 (glutathione peroxidase 1)
Diseases named in the same sentence as GPX1 in open-access papers (continued):
Sharing a sentence is not in itself a finding about the gene and the disease.
cardiovascular disease (13 papers, 2007 to 2024). "Since the Pro198Leu polymorphism in the Gpx1 gene was previously reported to be associated with cardiovascular disease in diabetic subjects, we checked the distribution of this polymorphism in subgroups of CVD + and CVD − patients." (PMID 27592002, 2017). "It was found that selenium supplementation could protect the myocardium against oxidative stress damage by increasing the activity of GPx1; therefore, the risk of cardiovascular disease decreased." (PMID 24062877, 2013). "Experimental studies have shown a role for a subset of redox-active selenoproteins, including GPx1, GPx3, GPx4, and Txnrd2, in protecting against complex cardiovascular diseases, in part, by attenuating the harmful effects of reactive oxygen species." (PMID 34579115, 2021). "Glutathione peroxidase-1 (GPX-1) activity was reported to be useful marker for monitoring cardiovascular disease." (PMID 27229152, 2016).
inflammation (4 papers, 2012 to 2023). Aberrant reaction of the microcirculation characterized by movement of fluid and leukocytes from the blood into extravascular tissues. "To understand the basis for the paradoxical reduction of LPS-induced lung inflammation in gpx-1 deficient mice we assessed whether key cytokines and chemokines involved in the recruitment of inflammatory cells in response to LPS were affected." (PMID 22412999, 2012). "Clearly, GMP showed capacity in fighting OxS in the circulation (MDA and F2 isoprostanes) and liver (GPx1), and in alleviating liver inflammation, which is documented by a decline in inflammatory biomarkers (COX-2, TNF-α and IL-6)." (PMID 34572325, 2021). "Additionally, another group investigated the protective role of glutathione peroxidase 1 (GPx1) against acute lung inflammation induced by CS." (PMID 36978796, 2023).
kidney disease (4 papers, 2012 to 2024). "The association between GPX1 and decreased eGFRcrea highlights its critical role in kidney disease progression." (PMID 38892221, 2024). "Comparison of the Chow and HFD groups with regard to the levels of blood glucose, sizes of the kidneys and glomerulus, and levels of 8‐OHdG, GPX1, F4/80, and OPA1 indicated the successful development of NASH‐related kidney diseases." (PMID 31561285, 2019).
heart diseases (3 papers, 2018 to 2022). "Individuals with non-fatal MI and thosewho had died from cardiac diseases had significantly lower GPx-1 baselinelevels." (PMID 29257712, 2018).
metabolic disorder (3 papers, 2015 to 2016). "Increased understanding of tissue-specific functions of GPx1 will improve our knowledge of the role GPx1 plays in metabolic disease." (PMID 26861388, 2016). "Generally speaking, both GPx1 overexpression and deficiency appear to have negative effects in metabolic disease." (PMID 26861388, 2016). "Previous studies showed that long-term metabolic disorder affected the function of mitochondria, and decreased the activity of enzymatic antioxidant, such as SOD1 and GPX1." (PMID 25747866, 2015).
peripheral neuropathy (3 papers, 2017 to 2018). A disorder affecting the peripheral nervous system. "One of the possible pathophysiological mechanisms involved in Gpx1 role in peripheral neuropathy might be an impaired microcirculation in the peripheral nerves caused by vascular endothelial dysfunction associated with oxidative stress." (PMID 27592002, 2017).
psychiatric disorder (3 papers, 2020 to 2025). A disorder characterized by behavioral and/or psychological abnormalities, often accompanied by physical symptoms. "glutathione peroxidase 1 (GPx1) plays an important role in metabolic dopamine change and closely relates to neurological and psychiatric disorders." (PMID 33070477, 2020).
adenocarcinoma (1 paper, 2023). A common cancer characterized by the presence of malignant glandular cells. "We have found that the degree of histological differentiation and the immunohistochemical expression of Gpx-1 were independent prognostic factors for adenocarcinoma." (PMID 37242524, 2023).
bacterial infection (1 paper, 2023). "The transcriptional analysis of four antioxidant genes in L. rohita showed that, in the presence of bacterial infection, the expression of GPx-1 was more pronounced in the anterior kidney tissue compared to the remaining three antioxidant genes." (PMID 38275638, 2023). "The study observed a considerable up-regulation of GPx-1 expression during the initial stages of bacterial infection, specifically at 1 hpc and 3 hpc, which was subsequently followed by a down-regulation." (PMID 38275638, 2023). "From four antioxidants, three recombinant proteins, i.e., CAT, GPX-1, GST-mu, were studied for the relative percentage survival of L. rohita against bacterial infection; however, rLrCuZnSOD was found toxic to fish that needs further investigation." (PMID 38275638, 2023).
GPX1 also shares sentences with these, for which no sentence is quoted: neurodegenerative disease (4 papers); Chronic Myeloid Leukemia (3); meningioma (3); Nephropathy (3); rheumatoid arthritis (3); acute coronary syndrome (2); acute myocardial infarction (2); age (2); anemia (2); benign tumors (2); brain disease (2); brain injury (2); cerebral infarction (2); cyst (2); fibrosarcoma (2); Headache (2); liver fibrosis (2); lung disease (2); neurological disease (2); Parkinsons (2); acquired immunodeficiency syndrome (1); acute kidney injury (1); adenoma (1); adrenocortical tumor (1); alopecia areata (1); anaplastic thyroid cancer (1); Anxiety (1); Autoimmunity (1); bipolar disorder (1); bladder neoplasms (1).
A further 60 diseases each share a sentence with GPX1 in 1 paper.